INS (insulin)
Diseases named in the same sentence as INS in open-access papers (continued):
Sharing a sentence is not in itself a finding about the gene and the disease.
Hypoglycemia (continued). "Compared to hyperglycemic DKA patients managed in the same protocolized fashion, euglycemic DKA patients were on insulin infusions 5.9 hours less, yet experienced hypoglycemia over three times more frequently." (PMID 38165186, 2023). "Hypoglycemia is known to elevate mortality risk in the ICU, with intensive insulin therapy being a critical factor contributing to hypoglycemic events." (PMID 37764757, 2023). "This is of particular importance as dysglycaemia, particularly prolonged episodic hypoglycaemia, can masquerade as wilful insulin dose manipulation, sometimes with forensic or safeguarding implications." (PMID 37562398, 2023). "In insulin-treated T2D, this rate is one-third of that in T1D; besides, in both T1D and T2D, the rate of any type of hypoglycemia is ~50-fold higher than those of severe hypoglycemia." (PMID 38003671, 2023). "Diabetic patients can experience hypoglycemic events from medication use (iatrogenic hypoglycemia) either due to insulin, oral anti-diabetic agents (OADs), or incretin-based therapies." (PMID 37108651, 2023). "Acute approaches for preventing exercise-induced hypoglycemia include carbohydrate supplementation (CHOsup) and insulin reduction strategies." (PMID 37999431, 2023). "Experimental and clinical evidence was suggestive of diclofenac to increase insulin release from beta cells by inhibiting ATP-sensitive K-channels, and this provides a rationale for the observed hypoglycemia." (PMID 36674967, 2023). "The findings demonstrated that a low incidence of hypoglycemia during Ramadan was related to glucose-lowering medications such as insulin, sulfonylureas, and metformin." (PMID 38169925, 2023). "Rates of severe hypoglycemia were uncommon, occurring in patients additionally taking insulin or sulfonylureas." (PMID 37373620, 2023). "In the current study, case 1 presented Whipple’s triad accompanied by moderately increased insulin and C-peptide levels when hypoglycemia occurred." (PMID 36459334, 2023). "Hypoglycemia is a potential adverse effect though this is rare given the glucose-dependent mechanism and is usually seen in patients taking insulin or insulin secretagogues." (PMID 37526853, 2023). "High insulin levels enhance this uptake and suppress endogenous glucose production, which leads to hypoglycemia." (PMID 36964201, 2023). "Hypoglycemia is a common adverse effect of insulin therapy and an indicator that the safety of insulin requires evaluation." (PMID 37143729, 2023). "Insulin autoimmune syndrome (IAS), also known as “Hirata’s disease,” is a rare condition characterized by spontaneous hypoglycemia accompanied by the presence of insulin autoantibodies (IAA) in the blood, either fasting or postprandial." (PMID 37587407, 2023). "At discharge from hospitalization, health care personnel should ensure that the patient/family member learns the exact dosage, forms of insulin application, and alarm symptoms of hypoglycemia." (PMID 37377235, 2023). "The neurologist referred him to an endocrinologist physician who diagnosed insulinoma on the basis of inappropriately normal serum insulin and C-peptide concentrations during a spontaneous episode of hypoglycemia." (PMID 37308982, 2023). "BGAT equips people with T1D with comprehensive and practical content including insulin, dietary, physical activity, blood glucose management, and most importantly, its goal is to heighten an individual’s ability to detect and avoid hypoglycemia." (PMID 37942482, 2023). "Diabetic individuals undertaking insulin should monitor blood glucose levels before, during, and after exercise sessions, in order to minimize complications such as hypoglycemia." (PMID 36593495, 2023). "In a retrospective analysis of late-stage CKD patients being treated with insulin (n = 221), 13% of patients developed hypoglycemia." (PMID 37016309, 2023).
Hypoglycemia (continued). "Our study agrees with previous work showing that high levels of glucose at 60 min related to impaired early-phase insulin secretion and consequently high levels of insulin at 120 min were seen in those with hypoglycaemia." (PMID 37720541, 2023). "In the NICE–SUGAR trial, patients who underwent intensive insulin therapy for tight glucose control had more frequent severe hypoglycaemias than patients in the control arm (6.8% vs 0.5%) and a significantly increased mortality (OR 1.14 [95% CI 1.02–1.28])." (PMID 37330419, 2023). "Studies have demonstrated neuroprotective effects for extracts of hot pepper in experimental models of Parkinson’s disease and insulin-induced hypoglycemia." (PMID 36865040, 2023). "The insulin degludec and glargine groups had significantly lower HbA1c (p = 0.002), hypoglycemia (p = 0.006), severe hypoglycemia (p = 0.029), and IDD (p = 0.015) than the NPH group." (PMID 36800034, 2023). "Their plasma glucose, insulin, and C-peptide levels were tested simultaneously when hypoglycemia occurred." (PMID 36459334, 2023). "The speaker also discusses differing carbohydrate needs for blood glucose maintenance and treatment of hypoglycemia depending on type of insulin delivery (injections, pumps, and hybrid-closed loop systems)." (PMID 37886638, 2023). "Basal insulin combined oral therapy is also accompanied by several benefits such as reduced insulin dose and injection frequency, and decreased hypoglycemia events and blood glucose monitoring as compared with basal-bolus insulin therapy." (PMID 36624650, 2023). "Null mutations in the PCSK1 gene can cause morbid obesity, hypoadrenalism, hypogonadism, bowel dysfunction, hyperphagia, impaired proinsulin-insulin ratio, postprandial hypoglycemia, and diabetes insipidus." (PMID 37954272, 2023). "In a study conducted on 12 patients with T2D, activation of platelets by hypoglycemia was reversed when measured 30 min after insulin-induced hypoglycemia." (PMID 36830610, 2023). "Insulin‐mediated hypoglycaemia increased carotid sinus nerve activity and ventilation, which partially offset the hypermetabolic effects of hypoglycaemia." (PMID 36602416, 2023). "After intravenous infusion of lipids, rabbits were found to be insensitive to insulin-induced hypoglycemia." (PMID 37867511, 2023). "Rivera and colleagues demonstrated in dogs that hypoglycemia and hyperglucagonemia markedly inhibit insulin action in the liver, making it only a fraction of that seen under euglycemic or hyperglycemic conditions." (PMID 37166980, 2023). "Hypoglycaemia occurred despite stopping insulin from 20.00 h to 07.00 h and consuming a snack (~50 g carbohydrate) before bed." (PMID 37562398, 2023). "The increased insulin levels due to hepatic bypass are incompletely degraded, leading to this hypoglycaemia." (PMID 37664849, 2023). "The diagnosis of insulinoma is confirmed by the presence of Whipple’s triad: clinical symptoms of hypoglycemia, biochemical evidence of endogenous insulin hypersecretion, and symptoms relief by the consumption of glucose." (PMID 37026903, 2023). "Empagliflozin has several adverse effects to be monitored for, including hypotension, ketoacidosis, acute kidney injury, genital mycotic infections, hypoglycemia when combined with insulin, a rare but serious Fournier gangrene, and pyelonephritis." (PMID 36961036, 2023). "Another case report described an 82-year-old man with type 2 diabetes using insulin detemir who experienced severe hypoglycemia during treatment for H. pylori infection." (PMID 37700268, 2023). "Similar commonly activated brain structures have been identified by Pacak and Palkovits using different stressors (immobilization, cold, insulin-induced hypoglycemia, hemorrhage and pain)." (PMID 37511494, 2023).
Hypoglycemia (continued). "We aimed to assess counter-regulatory hormones and glucose fluxes during insulin-induced postprandial hypoglycaemia in patients with post-bariatric hypoglycaemia after Roux-en-Y gastric bypass vs surgical and non-surgical control individuals." (PMID 36648553, 2023). "An insulin overdose can lead to hypoglycemia, with blood glucose levels below 3.9 mmol/L (70 mg/dL) defined as clinical hypoglycemia and blood glucose levels below 3 mmol/L (54 mg/dL) defined as clinically important hypoglycemia." (PMID 38250973, 2023). "This primary antidiabetic mechanism of EPE involves a significant enhancement of insulin-producing β cells (stimulation of β-cell secretion of insulin), thereby producing hypoglycemia." (PMID 37850072, 2023). "Post-exercise hypoglycemia occurred in five participants and was most frequent in those taking insulin and/or two or more anti-hyperglycemic medications." (PMID 36835790, 2023). "CGM alarms have helped pre‐empt hypoglycaemia, but weight has increased by 10 kg despite a reduction of insulin dose to 24 units/day." (PMID 37562398, 2023). "Complete absence of plasma membrane KATP channels due to null mutations of the KATP channel subunits, results in more extreme flattening of glucose-insulin response curve with very severe neonatal hypoglycemia (as well as glucose intolerance later in life)." (PMID 36969273, 2023). "Ability to monitor blood glucose at home helps prevent severe hypoglycemia and facilitates adjustment of insulin dosages as needed." (PMID 37291520, 2023). "The mothers of neonates with hypoglycaemia, prior to delivery, had high daily insulin requirements, which ranged between 58 units to 104 units." (PMID 36793288, 2023). "We previously reported that in mice, ghrelin is permissive for the usual CRR to insulin-induced hypoglycemia." (PMID 37334290, 2023). "It is diagnosed by detectable insulin and C-peptide levels, low beta-hydroxybutyrate, and low free fatty acids in the setting of hypoglycemia." (PMID 37404330, 2023). "In 1982, a study on insulin-induced hypoglycemia in juvenile diabetics found that an increase in fibrinogen and Factor VIII reduced activated partial thromboplastin time (PTT) and decreased platelet count to be associated with hypoglycemia." (PMID 36830610, 2023). "There is less weight gain, less hypoglycemia and lower insulin dose with premixed insulin analogues compared to basal-bolus therapy." (PMID 36882852, 2023). "Cattle exposed to shifts in light-dark phases during late pregnancy develop hypoglycemia and insulin resistance." (PMID 37727248, 2023). "Some of the most common adverse effects of insulin therapy include episodes of hypoglycemia, injection site reactions, lipodystrophy, weight gain, headache, and edema due to fluid retention." (PMID 37920618, 2023). "The role of growth hormone and cortisol in regulating the severity of hypoglycaemia during sustained intravenous insulin infusion was demonstrated in two studies by De Feo et." (PMID 38053731, 2023). "When combined with basal insulin, GLP-1 receptor agonists exhibit potent glucose-lowering effects while minimizing weight gain and hypoglycemia when compared with intensified insulin regimens." (PMID 37762856, 2023). "With a flexible four times daily insulin regimen (on average 0.8 units/kg daily), he suffered from recurrent hypoglycemia and poor glycemic control (HbA1c 90.3 mmol/mol Hb)." (PMID 37692453, 2023). "In our T2D real-world patients treated with a low-premixed insulin preparation, the average time spent in hypoglycemia was 33.1 min daily (2.3%), with 11.5 min in level 2 hypoglycemia." (PMID 36882852, 2023). "We aim to assess the level of knowledge about hypoglycemia and its management among insulin-requiring DM patients in Al-Ahsa, Saudi Arabia." (PMID 37859676, 2023).
Hypoglycemia (continued). "Hypoglycaemia due to exogenous insulin administration is easily distinguished from endogenous hyperinsulinaemia by inappropriately high insulin levels in the presence of low or suppressed C-peptide levels." (PMID 37892096, 2023). "In general, prandial insulin is injected two or three times daily before each meal, and glucagon injection is used to treat severe hypoglycemia." (PMID 36684080, 2023). "Since the threshold for starting insulin treatment in premature babies is set around 12 mmol/L and hypoglycaemia is defined as less than 2.5 mmol/L, there is a sufficient safety margin to titrate the insulin treatment to maintain normoglycemia." (PMID 38004396, 2023). "This rarely performed procedure provides results comparable to pancreas transplantation in terms of glucose control and avoidance of severe hypoglycaemia, but insulin independence rates are significantly lower after one year (31% vs 96% in SPK group)." (PMID 37176684, 2023). "This study compared the frequency of hypoglycaemia, time to hypoglycaemia and recovery from hypoglycaemia after double or triple doses of once-weekly insulin icodec vs once-daily insulin glargine U100." (PMID 37308751, 2023). "Seizures have been especially described in preschoolers with T1DM who experience hypoglycaemia due to excessive insulin intake." (PMID 37048663, 2023). "A major proportion of cases with DR used insulin (57.1%) and had severe hypoglycemia events in the year before this study (71.4%) compared to cases without DR (30.8%)." (PMID 37876724, 2023). "The adverse effects of insulin and oral hypoglycemics, such as hypoglycemia and gastrointestinal symptoms, also limited the use of those medications, and sometimes those treatments are more dangerous than hyperglycemia to the mother and fetus." (PMID 37049473, 2023). "Although most participants felt embarrassed by low blood sugar or hypoglycemia (56%) and by taking medication (i.e., insulin injection at school) (48.3%)." (PMID 37779730, 2023). "Plasma insulin and glucagon levels were low during fetal and neonatal life of TgPWS mice, and, at postnatal day 1 prior to onset of hypoglycemia, there was significantly reduced basal and glucose-stimulated insulin secretion (GSIS) from cultured TgPWS islets." (PMID 37068109, 2023). "The secretion of insulin decreases, avoiding the combination of a large amount of insulin with insulin autoantibodies, and improves the symptoms of postprandial hypoglycemia in patients with the autoimmune syndrome." (PMID 36844104, 2023). "This form of hypoglycemia is self-induced, through the administration of insulin or oral hypoglycemic drugs." (PMID 37629713, 2023). "Laboratory exam on admission demonstrated hypoglycemia accompanied with low serum insulin and IGF1 levels." (PMID 36742395, 2023). "The riskof hypoglycemia, which is of more clinical concern, was prominently low, with thebasal insulin reduction in the last four to five hours of fasting, in the twogroups." (PMID 34809475, 2023). "In I1 detectable plasma insulin was documented only once at 11 days of age (3.9 mU/L) at hypoglycaemia of 2.3 mmol/L." (PMID 37974153, 2023). "Side effects such as hypoglycemia and weight gain, along with insulin distress, have often impeded the adoption and reach of insulin to patients." (PMID 36650625, 2023). "It is possible that decreased insulin sensitivity in PS-treated cows reflected a peripheral tissue adaptation, with increased insulin resistance preventing hypoglycemia in response to lower gluconeogenic capacity of hepatic tissue." (PMID 37727248, 2023). "Hypoglycemia is a major side effect of some glucose-lowering therapies, in particular, insulin and the insulin secretagogues." (PMID 38001509, 2023). "Based on the development of the risk calculation model for severe hypoglycemia, the score for the history of severe hypoglycemia, eGFR less than 60 mL/min/1.73 m2, and insulin use were 2, 1, and 1, respectively." (PMID 37758787, 2023).
Hypoglycemia (continued). "In patients with EHH, we should primarily identify the etiology according to their clinical symptoms, blood glucose, serum insulin, C-peptide, relevant antibodies, and imaging examination, to provide effective treatment and eliminate hypoglycemia." (PMID 36459334, 2023). "As a result, imperfect dosing can lead to a state of relative hyperinsulinemia (i.e., excess systemic insulin levels relative to blood glucose concentration), in which glucose counterregulatory mechanisms become critical to protecting against hypoglycemia." (PMID 38298268, 2023). "Nevertheless, heterogeneous relationship between the glucagon response to insulin-induced hypoglycemia does exist but again is most evident in T1D with high levels of residual C-peptide." (PMID 36935525, 2023). "A well-controlled trial of modest hypoglycemia in humans using an insulin clamp led to the appearance of tactile hyperalgesia and transient autonomic failure related to the discharge of pro-inflammatory cytokines." (PMID 37513978, 2023). "This molecule normalised blood glucose in diabetic models, and was markedly less prone to induce hypoglycaemia than conventional insulin treatment (approximately 4.6-fold less potent under hypoglycaemic conditions than under normoglycaemic conditions)." (PMID 36404376, 2023). "The DCCT itself demonstrated how the intensity of insulin treatment was accompanied by an increase in the frequency and severity of hypoglycaemia, and at the same time, by a progressive increase in weight in the intensively treated group." (PMID 37685946, 2023). "Family members of younger patients described accompanying PLWT1D to clinic visits, checking BG levels, injecting insulin, and performing other self-management activities for them in instances of hyper- or hypoglycemia." (PMID 37291520, 2023). "In dogs, NaCN‐mediated CSN activity and cardiorespiratory responses were significantly augmented during insulin‐induced hypoglycaemia." (PMID 36459572, 2023). "Case reports suggest that severe hypoglycemia due to excess insulin administration contributed to these deaths." (PMID 37887414, 2023). "Because β-cells sense blood glucose levels and determine the amount of insulin to be secreted, during hypoglycemia, insulin secretion is inhibited, resulting in insulin accumulation in β-cells." (PMID 38132137, 2023). "Earlier studies recorded an increase in platelet aggregation following insulin-induced hypoglycemia for at least 2 h following the induction of hypoglycemia." (PMID 36830610, 2023). "Previous studies suggest that large glucose fluctuations and hypoglycemia provide mechanistic links between insulin therapy and adverse clinical outcomes." (PMID 37194077, 2023). "In the male, levels of insulin and C‐peptide were suppressed and a diagnosis of paraneoplastic hypoglycemia by IGF‐2 secretion was made with increased glucose disposal in skeletal muscle proven by 18F‐FDG-PET-CT." (PMID 36703082, 2023). "As clinically relevant episodes of hypoglycaemia seem to happen rarely after the first week of life, the increased insulin production either normalises or becomes less clinically evident, through insulin resistance." (PMID 37442824, 2023). "Congenital hyperinsulinism (CHI) is a group of clinically, genetically, and morphologically heterogeneous disorders characterized by recurrent episodes of hyperinsulinemia and hypoglycemia due to dysregulated insulin secretion from pancreatic β-cells." (PMID 37056678, 2023). "After Roux-en-Y gastric bypass surgery for weight management, it is reported that, in addition to the increased β-cell response to oral stimuli, insulin-independent glucose disposal is also suggested to contribute to severe hypoglycemia." (PMID 36837857, 2023). "In general, when compared with basal insulin alone, premixed regimens tend to lower HbA1c to a more significant degree, but often at the expense of more hypoglycemia and weight gain." (PMID 36882852, 2023).